IL6 (interleukin 6)
Diseases named in the same sentence as IL6 in open-access papers (continued):
Sharing a sentence is not in itself a finding about the gene and the disease.
diabetes (continued). "Pro-inflammatory molecules such as VEGF, ICAM-1, MCP-1, IL-6, IL-8, and TNF were consistently detected at higher levels in the vitreous of diabetic patients compared to those without diabetes, and in PDR or diabetic macular edema (DME) patients compared to non-DR patients." (PMID 35802672, 2022). "In addition, a clinical cohort study revealed rather specific negative correlations between the serum sitosterol level and the serum IL6 and TNF-α levels in both subjects with and without diabetes, suggesting the anti-inflammatory potential of β-sitosterol." (PMID 33953784, 2021). "Nevertheless, the patients with acromegaly having diabetes had modestly higher CAL and PD and serum IL-6 levels (p = 0.051), but it could not exert adverse effects on periodontal health in presence of GH/IGF1 excess." (PMID 33154456, 2020). "Already after 4 weeks of diabetes, a time-point when no changes in aortic plaque size had yet occurred, expression of VCAM-1, MCP-1, IL-1β, Cox2, TF and maybe also IL-6 and ICAM-1 (borderline significance) were higher than in control non-diabetic mice." (PMID 23755169, 2014). "Although contradictory results have been demonstrated that diabetes did not affect RANKL expression, other authors showed that diabetic mice presented decreased bone density accompanied by higher levels of RANKL, IL-1, and IL-6." (PMID 22611374, 2012). "ARBs also have anti-inflammatory effects as seen by lowering effect on plasma TNF-α and IL-6 levels in patients with diabetes and hypertension Telmisartan, but not valsartan, was shown to attenuate TNF-α induced IL-6 production by vascular smooth muscle cells in a PPAR-γ dependent manner." (PMID 21276223, 2011). "In the present study we found that TNFα−/− deficient mice exhibited higher basal levels of VCAM-1 protein in retinal vessels and sVCAM-1 in plasma than wt mice, but these mice failed to up-regulate IL-6 and IL-1β mRNA and VCAM-1 protein in response to diabetes." (PMID 20856927, 2010). "A higher IL-6/IL-10 ratio was found in patients with diabetes than the values observed in the group without diabetes at T0 (p = 0.029) and T1 (p = 0.025), whereas an increased IFN-γ/IL-10 ratio was only found at T1 in patients with diabetes compared to the group without diabetes (p = 0.041)." (PMID 39253540, 2024). "However, the results from the ADVANCE Study showed that IL-6 levels, a circulating inflammatory marker, rather than CRP or fibrinogen levels, were an independent predictor of macrovascular events and mortality in patients with diabetes." (PMID 37775767, 2023). "In a study of SRP in periodontal patients with diabetes, it was reported that there was no change in HbA1c and serum biomarkers (hs-CRP, TNF-α, IL-6) during the 6-month follow-up period, regardless of whether SRP was performed and the severity of periodontal disease." (PMID 36140045, 2022). "There were no considerable differences in gender, current smokers, diabetes history, cardiovascular disease history, and WBC between the mild and severe group, while significant differences were observed in age, LYM, and serum levels of CRP, ESR, IL-6, D-dimer, and lactic acid." (PMID 34344306, 2021). "Our results indicate that susceptibility to NODAT might be monitored by genotyping KTRs who developed diabetes compared with KTRs who did not develop diabetes for selected major Th 1(IFNG)/ Th-2 (IL-4)/TGFB, T-reg in addition to IL-6, macrophage derived cytokines." (PMID 33727573, 2021). "One study in type 2 diabetes mellitus (T2DM) patients demonstrated that Propolis at a dose of 1000 mg/ day administration for 3 months, significantly decreased hs-CRP and TNF-α levels but had no significantly difference seen for the serum IL-1β and IL-6 levels." (PMID 32817750, 2020).
diabetes (continued). "While diabetes is a complex disease, and STAT3 can be phosphorylated by many cytokines that utilize the gp130 receptor, it appears that hyperglycemia (but not hyperosmolarity) is sufficient to increase IL-6-induced STAT3 phosphorylation in keratinocytes in vitro." (PMID 31073533, 2019). "There is overwhelming evidence highlighting the critical role of IL-6 in facilitating wound healing; however, not much information is available on the temporal variations in IL-6 expression in diabetic wounds or on the involvement of p38 MAPK or PI3K/Akt signaling pathways in diabetes." (PMID 28542434, 2017). "Therefore, we aimed to investigate the prospective associations of baseline levels of biomarkers of subclinical inflammation [hsCRP, IL-6, IL-1 receptor antagonist (IL-1Ra)] and adiponectin with subsequent 5-year changes in HR and HRV in individuals with and without diabetes in large cohort." (PMID 29195493, 2017). "Interestingly, in those with both diabetes and LF, the pro-inflammatory cytokines - TNF-α, IL-6 and GM-CSF were reduced, compared to those without LF, suggesting that LF-mediated reduction of pro-inflammatory cytokines negatively influences the development of IR." (PMID 20559443, 2010). "And it has been widely confirmed that in patients with diabetes, after receiving GLP-1 receptor agonist treatment, the level of IL-6 decreases and pancreatic islet function improves, suggesting that GLP-1 may affect the function of pancreatic islets through the negative feedback of IL-6." (PMID 39235859, 2024). "Moreover, other variables that could reflect the effect of DHA supplementation, particularly improvements in macular function, TAC, or IL-6 levels, were not measured, as the present study was focused on the assessment of progression of any pre-proliferative stage of NPDR in patients with diabetes." (PMID 35052620, 2022).
breast cancer (1,892 papers, 1999 to 2026). A primary or metastatic malignant neoplasm involving the breast. "In the RATHER cohort of 79 ER + ILC patients with associated survival data, Hallmark IL6-JAK-STAT3 signaling was associated with better breast cancer specific survival." (PMID 40597443, 2025). "We recently reported that elevated serum interleukin‐6 (IL‐6) level in patients with breast cancer is associated with poor prognosis during eribulin therapy." (PMID 41189442, 2025). "Based on receiver operating characteristic (ROC) curve analysis, interleukin-6 (IL-6) was found to exhibit significant diagnostic performance for breast cancer (0.825, 95% confidence interval: 0.549–0.94, P = 0.030)." (PMID 41450733, 2025). "CAAs are defined as high producers of CXCL8, CCL2, and IL-6 associated with breast cancer development." (PMID 40076892, 2025). "Resistance to radiotherapy in breast cancer is also facilitated by the cytokine IL-6, which is recognized for its pro-inflammatory properties and is overexpressed in numerous cancers, especially by adipocytes associated with breast cancer." (PMID 41011273, 2025). "Elevated levels of inflammatory markers, such as Tumor Necrosis Factor-α (TNF-α), Interleukin-6 (IL-6), and neutrophils, have been observed in HR-positive breast cancer patients, suggesting their potential role as diagnostic indicators." (PMID 40906676, 2025). "Correlation analysis between plasma cytokine levels and clinicopathological features revealed that elevated levels of IFN-γ, IL-1β, IL-2, IL-6, and IL-12 (p40) were significantly associated with advanced clinical stages of breast cancer (P < 0.05)." (PMID 40612845, 2025). "For instance, elevated IL-6 levels have been associated with reduced survival in patients with HER2-positive breast cancer." (PMID 40558287, 2025). "Enhanced serum levels of IL-6 and IL-8 in breast cancer patients was associated with advanced clinical disease stage, lymph node metastasis, and poor prognosis." (PMID 40507273, 2025). "This vaccine works by targeting IL-6, which is particularly high in breast cancer and is associated with immunosuppressive effects in the TME." (PMID 40805190, 2025). "It has been associated with reduced interleukin-6 and tumor necrosis factor-α levels and anti-tumor activity in breast cancer xenograft models." (PMID 40731923, 2025). "In the context of breast cancer survivors, exercise-mediated reductions in proinflammatory biomarkers such as IL-6, TNF-α, and CRP have been linked with lower mortality, reduced recurrence risk, and lower hospitalization rates." (PMID 41303335, 2025). "Recent research has shown that elderly breast cancer patients and animal models have higher levels of IL-6, which are linked to frailty and the tumor progression process." (PMID 40584290, 2025). "IL-6 has been implicated in numerous protumoral effects in breast cancer, including promotion of metastasis by hijacking ER transcriptional program, CSC maintenance and chemoresistance, and recruitment of myeloid-derived suppressor cells (MDSCs)." (PMID 38236642, 2024). "Elevated serum levels of IL-1 and/or IL-6 in patients are usually associated with poor prognosis and poor survival of breast cancer patients." (PMID 38534756, 2024). "It has been suggested that the inhibitory effect of MPA on IL-6 secretion from breast cancer cells causes the anticachectic effect of MPA." (PMID 38956273, 2024). "Targeting iron disrupts the interaction between breast cancer cells and tumour‐associated macrophages, blocking the IL‐6 signalling pathway, and ultimately overcoming chemoresistance." (PMID 38140764, 2024). "An association between IL-6 and memory has also been observed in cross-sectional studies in patients with breast cancer." (PMID 38840166, 2024). "Chemoresistance in breast cancer was caused by pharmacological inhibitors of the Hedgehog pathway that increased IL-6 expression by macrophages." (PMID 38280079, 2024).
breast cancer (continued). "IL-6 is known to promote invasiveness through epithelial-to-mesenchymal transition and is associated with the formation and maintenance of breast cancer stem cells." (PMID 38397942, 2024). "IL-6 is a proinflammatory cytokine that has been implicated in promoting breast cancer metastasis by activating the notable JAK/STAT3 signaling pathway." (PMID 38255791, 2024). "Recent data indicate that IL-6 secreted by cancer-associated fibroblasts in a mouse model of human breast cancer MDA-MB-231 induces tumor radioresistance, confirming our observations in vitro." (PMID 37371868, 2023). "IL-6 expression in 249 patient serum samples was significantly increased, and this was associated with the recurrence risk of breast cancer." (PMID 38201482, 2023). "A previous study reported that high serum IL6 concentration was associated with poor prognosis of breast cancer patients." (PMID 37454220, 2023). "In breast tumors, IL6 is secreted via CAAs, which play essential roles in favor of proliferation, angiogenesis, dissemination, invasion, and metastasis of breast cancer, and its production is associated with therapy resistance." (PMID 37681908, 2023). "M2d cells are a source of IL-6 that is implicated in various tumor types such as ovarian cancer, breast cancer, gastric cancer, colorectal cancer as well as hepatocellular cancer." (PMID 37108657, 2023). "Observational studies have indicated that increased levels of inflammatory cytokines, specifically IL-6, are linked to a greater risk of recurrence and metastasis in early breast cancer patients who are HER2-negative." (PMID 37910571, 2023). "IL-6 has been associated with malignant properties of breast cancer stem cells via the induction of epithelial-to-mesenchymal transition and cell migration and invasion, enabling the establishment of metastasis." (PMID 38136303, 2023). "In particular, IL-6 and its associated signaling can promote breast cancer progression and metastasis." (PMID 37880751, 2023). "Current understanding proposes that CAFs in HER2+ breast cancer confer resistance to Herceptin by orchestrating the loss of PTEN or activating the IL-6/STAT-3/NF-κB signaling pathway." (PMID 38001753, 2023). "Since IL-6 is known to be associated with TRZ resistance in HER2+ breast cancer, we sought to analyze the expression levels of IL-6 in TRZ_S and TRZ_R derived from the parental BT474 cells." (PMID 36979654, 2023). "IL-6 has been shown to be secreted by cancer-associated adipocytes, leading to both increased angiogenesis and breast cancer proliferation." (PMID 37760470, 2023). "In pre-treatment studies, IL-6 was significantly associated with increased deficit accumulation frailty (Balducci and Leuven Oncogeriatric Frailty Score) in breast cancer." (PMID 37213604, 2023). "Upon analysis of the immune mediators of the tumor, we saw significant downregulation of pathological inflammatory signaling of IL-6 and IL-1beta, which are each implicated in breast cancer tumor growth and progression." (PMID 38203396, 2023). "IL-6 is implicated in various tumor types for promoting tumor growth such as ovarian cancer, breast cancer, gastric cancer, colorectal cancer as well as hepatocellular cancer." (PMID 37108657, 2023). "Induction of IL-6 can increase the tumor stage with lymph node involvement, recurrence risk, and distant metastasis in breast cancers." (PMID 36979654, 2023). "This is in agreement with studies that reported decreased IL-6 levels due to therapy and a relapse of body weight loss in complicated breast cancer patients." (PMID 36903346, 2023). "In breast cancer, it has also been observed that interlukin -6 (IL-6), secreted by breast cancer-associated MSCs, protected cancer cells from cisplatin-induced apoptosis by activating the signal transducer and activator of the transcription 3 (STAT3) pathway." (PMID 37175439, 2023).
breast cancer (continued). "Particularly in breast cancer cells, the activation of the NF-κB/IL-6/STAT3 pathway has been associated with a pro-tumoral response, by regulating downstream genes that control cell proliferation and angiogenesis." (PMID 36672332, 2023). "By analyzing data from patients with benign and malignant breast tumors, an association was found with serum levels of IL-6, IL-17 and VEGF." (PMID 36531035, 2022). "Several tumor cells, including breast cancer cells, can secrete IL-6, the upregulation of which is generally associated with poor prognosis and a low survival outcome." (PMID 35960749, 2022). "The association of IL-6 expression and breast cancer bad prognosis would not only be due to its relevance in tumor cell motility and epithelial-to-mesenchymal transition (EMT), but also to its essential role in cancer stem cell (CSC) self-renewal." (PMID 35163731, 2022). "For example, senescent osteoblasts that secrete IL-6 cause increased bone resorption, which leads to a more suitable environment for breast cancer cells to metastasize." (PMID 36497411, 2022). "Evidence of IL-6 release from a wide range of cell types and its association with breast cancer progression has been confirmed over the years and it has been described in different review articles." (PMID 35163731, 2022). "It has been reported that elevated levels of inflammation-related markers CRP, TNF, IL-6, and IL-8 are associated with poor prognosis in breast cancer patients." (PMID 36467500, 2022). "In this study among Italian women, a positive association was reported between circulating IL-6 levels and breast cancer risk independently from overall adiposity." (PMID 35948877, 2022). "For the ER+ and HER2-Neu breast cancer subtypes, IL-6 has been increasingly linked to acquisition of resistance and escape from specific therapies applied in these subtypes." (PMID 35163731, 2022). "Increased IL-6 levels can be a result of single nucleotide polymorphisms (SNPs) in the promoter region of IL-6 gene, and have been demonstrated to predict poor prognoses in breast cancer patients." (PMID 35371975, 2022). "Loss of let-7, which usually targets IL-6, causes IL-6 accumulation, which then induces NF-kB, thereby creating a positive feedback circuit that sustains human breast cancer cells in a transformed state." (PMID 35757000, 2022). "When adjusting the univariate model for waist circumference, instead of BMI, the association of IL-6 and breast cancer risk was attenuated (ORper SD increment = 1.24 (1.07–1.44); ORQ4vsQ1 = 1.32 (0.90–1.95), P-trend = 0.06)." (PMID 35948877, 2022). "It has been indicated the association between serum IL-6 levels and poor clinical outcomes of breast cancer patients." (PMID 35251985, 2022). "The positive association between IL-6 and breast cancer risk is in line with the only prospective study of biomarkers of chronic inflammation and risk of premenopausal breast cancer we identified." (PMID 35948877, 2022). "Over the years, IL-6 has been increasingly linked to the acquisition of ET resistance in breast cancer patients." (PMID 35163731, 2022). "While the association with IL-6 was consistent across different breast cancer subtypes and tumor sizes, the association with TNF-α was limited to larger tumors." (PMID 35948877, 2022). "Correspondingly, higher IL-6 levels in breast cancer patients were associated with major depressive disorder." (PMID 36275706, 2022). "IL-6 is similarly associated with STAT3-mediated cisplatin resistance in breast cancer, and with acquired cisplatin resistance and poor prognosis in head and neck squamous cell carcinoma." (PMID 35356749, 2022). "Another study included 1,380 patients with early-stage invasive breast cancer revealed that high IL-6 expression is associated with better disease-free survival and breast cancer specific survival." (PMID 35924148, 2022).